GJB2 (gap junction protein beta 2)
Description:
Structural component of gap junctions. Gap junctions are dodecameric channels that connect the cytoplasm of adjoining cells. They are formed by the docking of two hexameric hemichannels, one from each cell membrane. Small molecules and ions diffuse from one cell to a neighboring cell via the central pore.
Synonyms: Cx26; NSRD1; BAPS; DFNA3; DFNA3A; DFNB1; DFNB1A; HID; KID; PPK
Tractability: Small molecule: a structure with a bound ligand is known; a high-quality ligand is known; it has a binding pocket of medium quality. Antibody: UniProt places it where antibodies can reach, with high confidence; its Gene Ontology location is reachable by antibodies, with high confidence; UniProt predicts a signal peptide or a membrane-spanning region. PROTAC: ubiquitination databases record sites on it; a small molecule that binds it is known.
Gene: Protein-coding gene on chromosome 13 (20,187,463 to 20,192,980, reverse strand). Ensembl gene ENSG00000165474.
Subcellular location: Cell membrane; Cell junction, gap junction
Subcellular location (Human Protein Atlas): Mitochondria
Pathways (Reactome):
Vesicle-mediated transport: Gap junction assembly; Oligomerization of connexins into connexons; Transport of connexins along the secretory pathway; Transport of connexons to the plasma membrane
Gene Ontology:
Molecular function: calcium ion binding; gap junction channel activity; gap junction channel activity involved in cell communication by electrical coupling; identical protein binding; protein binding
Biological process: gap junction assembly; gap junction-mediated intercellular transport; transmembrane transport; cell-cell signaling; inner ear development; cell communication; cell communication by electrical coupling
Cellular component: connexin complex; gap junction; plasma membrane; endoplasmic reticulum-Golgi intermediate compartment
Genetic constraint (gnomAD): Loss-of-function variants: 30 observed, 16.86 expected, observed/expected ratio (o/e) 1.78, 90% interval 1.29 to 1.97. The upper end of that interval is the gene's LOEUF score, 1.97, which puts it in group 6 of 6, group 1 being the genes least tolerant of losing a copy. Missense variants: 284 observed, 305.24 expected, observed/expected ratio (o/e) 0.93, 90% interval 0.84 to 1.03. Synonymous variants: 123 observed, 125.26 expected, observed/expected ratio (o/e) 0.98, 90% interval 0.85 to 1.14.
Gene-disease validity (ClinGen):
ClinGen rates the evidence that GJB2 causes each of these diseases.
hearing loss disorder (autosomal dominant): Definitive. A partial or complete loss of hearing in one or both ears.
nonsyndromic genetic hearing loss (autosomal recessive): Definitive.
Homologues: Orthologues: chimpanzee GJB2 (100% identical), dog GJB2 (99% identical), macaque GJB2 (98% identical), pig GJB2 (96% identical), rabbit GJB2 (96% identical), rat Gjb2 (94% identical), mouse Gjb2 (93% identical), guinea pig GJB2 (90% identical), tropical clawed frog gjb2 (73% identical), zebrafish gjb8 (66% identical). Paralogues in human: GJB6 (77% identical), GJB1 (64% identical), GJB3 (52% identical), GJA8 (50% identical), GJB4 (50% identical), GJA3 (49% identical), GJA4 (48% identical), GJB5 (48% identical), GJB7 (47% identical), GJA1 (47% identical), GJA9 (46% identical), GJA10 (46% identical), and 8 more.
Diseases named in the same sentence as GJB2 in open-access papers:
GJB2 is named in the same sentence as 294 diseases in open-access papers, as found by Europe PMC text mining. Sharing a sentence is not in itself a finding about the gene and the disease. The quoted sentences say what the papers report.
hearing loss (417 papers, 2005 to 2026). "Overall, GJB2 hearing loss remains the most common cause of genetic HL worldwide, with over 400 variants and a broad phenotypic spectrum spanning from late onset mild impairment to profound congenital deafness." (PMID 41516362, 2026). "Clarifying the molecular pathophysiology and phenotypic spectrum of GJB2-related hearing loss is essential to define the natural history of GJB2 deafness and lay the clinical foundation for future gene, cell, and drug-based therapeutics." (PMID 41516362, 2026). "Continued collaboration across molecular genetics, auditory neuroscience, and clinical otology will be essential to translate these discoveries into accessible cures for those with GJB2 hearing loss." (PMID 41516362, 2026). "Recent advances in molecular therapeutics have presented new and innovative avenues for the correction of GJB2-related hearing loss." (PMID 41516362, 2026). "Disruptions in these processes by GJB2 variants lead to impaired cochlear homeostasis and sensorineural hearing loss." (PMID 41516362, 2026). "In a combined cohort of 234 individuals with biallelic GJB2 mutations, mild (4.5%) and moderate (13.3%) hearing loss accounted for only a small fraction of cases, whereas 14.9% exhibited severe hearing loss, and the majority (25%) had profound deafness." (PMID 41516362, 2026). "Gap junction Beta 2 Protein (GJB2, Connexin26, Cx26), the primary genetic cause of hereditary hearing loss (25%-50% of cases), has been exclusively regarded as forming an intercellular channel that mediates rapid communication." (PMID 41514193, 2026). "Mutations in gap junction protein β-2 (GJB2), encoding Connexin 26 (Cx26), are the most common genetic cause of hearing loss, responsible for up to 50% of inherited non-syndromic cases worldwide." (PMID 42278361, 2026). "A high proportion of autosomal recessive non-syndromic hearing impairment is linked to the GJB2 (OMIM 121011) gene which encodes for a gap junction protein, connexin-26." (PMID 42074586, 2026). "Genotype-phenotype correlations revealed that GJB2 variants were primarily associated with mild to moderate hearing loss, whereas SLC26A4 variants correlated with severe to profound phenotypes in the Singaporean populations." (PMID 41897287, 2026). "The high prevalence of GJB2 mutations across diverse populations has made this gene an essential part of molecular testing for hereditary hearing loss." (PMID 41516362, 2026). "In our study, we performed a comprehensive analysis of a genetic family to uncover the connection between the GJB2 c.551G>A mutation and syndromic hearing loss, concentrating on the phenotypic traits and inheritance patterns observed within this family." (PMID 40336802, 2025). "This strategy offers a potential therapeutic approach for addressing hereditary sensorineural hearing loss associated with GJB2 mutations." (PMID 40365300, 2025). "GJB2-related hearing loss is the most common type of genetic deafness worldwide, yet no drug or GJB2-targeted treatment is available." (PMID 40059830, 2025). "Historically, molecular genetic testing for hearing loss has prioritized sequencing of the GJB2 (connexin-26) gene, which is the most common genetic cause of congenital, nonsyndromic, mild to profound bilateral sensorineural hearing loss (OMIM #220290)." (PMID 41367487, 2025). "Up to now, the GJB2 c.551G>A variant has been linked to autosomal dominant non-syndromic hearing impairment, with only a single case previously reported involving autosomal dominant syndromic hearing loss." (PMID 40336802, 2025). "Despite the identification of these mutations, there are currently no effective interventions targeting the underlying pathogenesis of GJB2-associated hereditary hearing loss 8-16." (PMID 40365300, 2025).
hearing loss (continued). "Our findings define the audiological profile of children with biallelic GJB2 mutations and underscore the necessity of integrating genetic screening with sustained audiological follow-up for the early detection of hearing loss." (PMID 41440806, 2025). "Given the common occurrence of GJB2 p.V27I and GJB2 p.E114G, further research is warranted to determine their clinical relevance in hearing loss pathogenesis." (PMID 40943139, 2025). "Pathogenic variants contributing to GJB2-related hearing loss can include deleterious missense and truncating variants as well as large deletions upstream of GJB2's coding region that abolish essential regulatory elements necessary for GJB2 expression." (PMID 41367487, 2025). "This comparative overview revealed notable differences in variant frequencies between populations, underscoring the unique genetic architecture of GJB2-related hearing loss in Taiwan." (PMID 40943139, 2025). "Currently, screening for the GJB2 gene is considered a standard and first-line approach in diagnosing genetic hearing loss." (PMID 40981390, 2025). "Newborn audiological screening identified hearing loss in 20/35 (57%) of children in this cohort (14/27 52% GJB2‐HL; 6/8 75% SLC26A4‐HL) and all 20 children were referred based on findings in both ears." (PMID 40008839, 2025). "Despite high human prevalence of GJB2‐associated hearing impairment and small gene size, several preclinical models have outlined a number of challenges for putative translation." (PMID 40927552, 2025). "The GJB2 c.250G>A variant is generally thought to be associated with post-lingual, severe to profound hearing loss, but there have been reported that this mutation lead to mild hearing loss and skin keratoderma syndromic deafness." (PMID 40336802, 2025). "Aside from GJB2, the remaining landscape of genetic causes of hearing loss is heterogeneous, with curation efforts finding at least 100 definitively or strongly associated genes and around 60% of which display autosomal recessive (ARHL) inheritance." (PMID 41367487, 2025). "The provincial expanded Newborn Screening Program has good overlap with genetic findings in our clinical population with GJB2‐related hearing loss but captures only a small proportion of children in this region with variants in SLC26A4." (PMID 40008839, 2025). "This study expands the spectrum of GJB2 pathogenic variants causing hearing loss, and it is of concern to GJB2 screening methods that rely primarily on sequencing its coding region." (PMID 40981390, 2025). "Although genetic-molecular studies conducted in Mexico to determine the etiology of congenital hearing loss are scarce, they have detected the presence of homozygous or compound heterozygous pathogenic variants in the GJB2, GJB6, SLC26A4, and CDH23 genes." (PMID 40981390, 2025). "Here, we explore the utility of GS and ES on a historical cohort of hearing loss patients (2003–2011) that received only GJB2 sequencing and were carriers of a single, apparently pathogenic variant." (PMID 41367487, 2025). "Before conducting genetic testing on patients with hearing loss, we performed a prescreening for pathogenic variants in GJB2 and SLC26A4, the two most prevalent causative genes for nonsyndromic hearing loss in Korean individuals." (PMID 40164689, 2025). "Analysis revealed that among individuals with homozygous variants at the GJB2 locus (c.109G > A p.Val37Ile), 65% (11/17) experienced congenital hearing loss, while 35% (6/17) developed delayed hearing loss." (PMID 39757988, 2025). "GJB2 mutation has been identified as a significant genetic factor contributing to non-syndromic hearing impairment, accounting for a range of 13–42% of cases." (PMID 40092730, 2025). "In our study, 29 cases of recessive disorders were identified, the majority being sensorineural hearing loss caused by mutations in GJB2 (OMIM: 220290)." (PMID 41329681, 2025).
hearing loss (continued). "Rationale: The GJB2 gene, which encodes connexin 26 (Cx26), is recognized as the leading cause of non-syndromic hereditary hearing loss." (PMID 40365300, 2025). "Digenic inheritance of non-syndromic hearing loss caused by GJB2 and GJB3 or GJB6 has been described." (PMID 40121402, 2025). "Chinese Llama3.1:70b identified the GJB2 gene mutation–linked nonsyndromic hearing loss, a common cause in China due to widespread prenatal deafness gene screening and internet-based information." (PMID 40532199, 2025). "Although GJB2 mutations represent the predominant genetic cause of hereditary hearing loss, the corresponding mutant proteins exhibit detectable aggregation, particularly at cell–cell junctions, suggesting at least partial trafficking to the plasma membrane." (PMID 40943139, 2025). "Thirty‐five children with GJB2 and SLC26A4‐associated hearing loss were identified by NGS (n = 27 GJB2‐HL; n = 8 SLC26A4‐HL)." (PMID 40008839, 2025). "Research indicates that family members with p.R75W/c.235delC, where GJB2 c.235delC can cause autosomal recessive non-syndromic deafness, manifest more severe hearing loss and palmoplantar keratoderma than those with only the p.R75W mutation." (PMID 40336802, 2025). "The GJB2 c.109G > A variant was detected 78 times, a finding consistent with its known association with mild and late-onset hearing loss in Asian populations." (PMID 40421383, 2025). "Deleterious variants in GJB2 in humans are associated with congenital severe to profound hearing impairment." (PMID 40927552, 2025). "For instance, mutations in the core promoter of the GJB2 gene are a major cause of non-syndromic recessive hearing loss, and whole-genome sequencing has underscored the close link between GJB2 promoter mutations and hearing loss." (PMID 40989420, 2025). "Overall, 5/20 patients who were carriers of a pathogenic GJB2 variant had an alternative genetic diagnosis associated with their hearing loss." (PMID 41367487, 2025). "To date, over 130 distinct GJB2 mutations associated with hearing loss have been identified in clinical settings." (PMID 40365300, 2025). "Mutations in GJB2 (connexin 26), mitochondrial DNA variants, and other deafness-associated loci elevate vulnerability to early-onset sensorineural hearing loss." (PMID 41463124, 2025). "In this study, we document a family affected by GJB2-related prelingual severe to profound hearing loss, in which the proband also manifests characteristics of syndromic hearing impairment, including xeroderma and nail dystrophy." (PMID 40336802, 2025). "In recent years, the increasing application of genetic testing technologies has broadened the spectrum of the association between GJB2 mutations and hearing loss." (PMID 41440806, 2025). "Pathogenic variants in the GJB2 gene, which encodes the intercellular gap junction protein connexin 26 (Cx26), are the main genetic factor associated with non-syndromic hearing loss, with spectra of variants varying among different ethnic groups." (PMID 40981390, 2025). "Children with two pathogenic or likely pathogenic variants of GJB2 or SLC26A4 were considered to have genetic hearing loss." (PMID 40008839, 2025). "AAV-mediated base editing therapy enables to repair effectively the pathogenic gap junction plaques (GJPs) and restore its physiological function in dominant-negative GJB2-related hearing loss." (PMID 40059830, 2025). "This study will increase the understanding of the genetic functional implications of hearing loss-related genes and clarify the pathogenesis of GJB2 related hearing loss and provide new insights and solutions for its prevention and protection." (PMID 40943139, 2025). "The identification of this novel large deletion expands the spectrum of GJB2 pathogenic variants causing non-syndromic hearing loss, and it is of concern to GJB2 screening methods that rely primarily on Sanger sequencing for its coding region." (PMID 40981390, 2025).
hearing loss (continued). "Genetic alterations causing GJB2 dysfunction are the most prevalent cause of hereditary hearing loss worldwide." (PMID 40565562, 2025). "Initially, many researchers regarded GJB2 p.I203T as a benign polymorphism, and its clinical impact on hearing impairment received little further investigation." (PMID 40943139, 2025). "We found another common mutation in Taiwan Biobank, GJB2 p.I203T, which were identified in our data and individuals carrying this mutation experienced more severe hearing loss, suggesting a synergistic effect of these mutations on auditory impairment." (PMID 40943139, 2025). "Hearing loss is a genetically heterogeneous sensory defect for which biallelic pathogenic variants in the GJB2 gene are a frequent cause." (PMID 40981390, 2025). "Multiple studies have established that GJB2 mutations confer a risk for delayed-onset or progressive hearing loss." (PMID 41440806, 2025). "Skin phenotypes associated with syndromic hearing loss due to GJB2 mutations encompass ichthyosis, palmoplantar keratoderma, joint pads, and nail abnormalities." (PMID 40336802, 2025). "In subjects with ichthyosis and hearing loss, the c.148G>A (D50N) mutation appears to be prevalent among patients with GJB2-related deafness, indicating a common pathogenic variant within the studied population." (PMID 40004458, 2025). "These five pathogenetic HDV loci are associated with the susceptibility of osteopetrosis (CLCN7), hearing loss (GJB2), cardiomyopathy (PRDM16), arrhythmogenic right ventricular dysplasia 1 (TGFB3), and sucrase-isomaltase deficiency (SI), respectively." (PMID 38448908, 2024). "The CDH23 gene, known for its association with hearing loss, harbors over 400 documented mutations that contribute significantly to non-syndromic hearing loss and are crucial for genetic screenings alongside genes like GJB2 and SLC26A4." (PMID 39596651, 2024). "The major genetic causes of integral hearing loss are GJB2 and SLC26A4, while specific AN is totally different." (PMID 38456936, 2024). "The refinement of the cis-regulatory element of GJB2 is of importance in elucidating the mechanisms of GJB2-related nonsyndromic hearing loss, which represents the most prevalent form of hearing loss." (PMID 40225913, 2024). "There are several papers reporting NGS analysis results for hearing loss patients; however, many of them pre-screened GJB2- or SLC26A4-associated HL cases, making it difficult to estimate the true prevalence of MYO7A-associated HL." (PMID 38594301, 2024). "GJB2 gene mutations account for more than 50% of cases of sensorineural hearing loss due to autosomal recessive inheritance and 20% of cases of prelingual hearing loss in high-income countries." (PMID 39442262, 2024). "These include MUTYH and colorectal cancer, GJB2 and hearing loss, and a pleiotropic association of FLG with both dermatitis and asthma." (PMID 38944039, 2024). "In our population, the five patients who had GJB2 mutations with simple heterozygosis showed the mildest degree of hearing impairment, with an average PTA of 50.38 ± 27.59 dB." (PMID 38397306, 2024). "The positivity rates of GJB2 c.235delC, c.299_300delAT, and c.176-191del16 were 23.3, 10.3, and 4.3%, respectively, in patients with non-syndromic hearing loss in the present study cohort from Changzhou." (PMID 38172427, 2024). "Patients with nonsyndromic hearing loss who appeared to have two GJB2 pathogenic variants, including the R143W variant, were investigated." (PMID 38730444, 2024). "Despite these advances, in Latin America, the population with hearing loss remains underdiagnosed, with most studies focusing on a single locus encompassing the GJB2/GJB6 genes." (PMID 38397168, 2024). "The segregation and expression data strongly support the role of the 125 kb deletion as a pathogenic factor in GJB2-related hearing loss." (PMID 40225913, 2024).